DNMT3A (DNA methyltransferase 3 alpha)
Diseases named in the same sentence as DNMT3A in open-access papers (continued):
Sharing a sentence is not in itself a finding about the gene and the disease.
ovarian carcinoma (continued). "Top anti-correlated genes of miR-29 in ovarian cancer included DNMT3A and DNMT3B, suggesting a similar role for miR-29 in high-grade serous ovarian cancer." (PMID 22479643, 2012). "De novo methyltransferase 3A (DNMT3A) was overexpressed in ovarian cancer tissues." (PMID 40868085, 2025). "DNMT3A was overexpressed in ovarian cancer tissues when compared with normal ovary tissues." (PMID 37110218, 2023). "Another research also demonstrated that miR-145 could target c-myc which interacted physically with DNMT3A in ovarian cancer cells, and inhibit the Warburg effect through miR-133b/PKM2 pathways." (PMID 32232409, 2020). "The clinicopathological correlation analysis of the DNMT3A level in ovarian cancer showed that the later the clinical stage, the higher the pathological grade, the higher the expression of YTHDF2, and the higher the expression of YTHDF2 in patients with metastasis." (PMID 32948220, 2020). "Interestingly, ovarian cancer progression is also accompanied by increased expression of enzymes responsible for DNA methylation, DNMT1 and DNMT3a, and expression levels correlate well with a poor prognosis of patients with ovarian cancer." (PMID 31426393, 2019). "Interestingly, knockdown of DNA methyltransferase 3A (DNMT3A) notably increased miR-199a-3p level and then attenuated the expression of DDR1 in ovarian cancer cells, which suggested that DNMT3A was responsible for the miR-199a promoter hypermethylation." (PMID 28743276, 2017). "Therefore, we evaluated the possible association of single nucleotide polymorphisms (SNPs) of DNA methyltransferases (DNMTs) genes, including DNMT1, DNMT3B, and DNMT3A, with ovarian cancer development in the Polish population." (PMID 23666104, 2013). "Haplotype analysis of DNMT1, DNMT3B, and DNMT3A polymorphisms did not reveal SNP combinations associated with the risk of ovarian cancer development." (PMID 23666104, 2013). "Furthermore, haplotype and multifactor dimensionality reduction analysis of the studied DNMT1, DNMT3B, and DNMT3A polymorphisms did not reveal either SNP combinations or gene interactions to be associated with the risk of ovarian cancer development." (PMID 23666104, 2013). "However, none of the other nine studied DNMT1, DNMT3B and DNMT3A SNPs exhibited significant association either in dominant or recessive inheritance models with ovarian cancer development." (PMID 23666104, 2013). "Furthermore, we aimed to study whether these DNMT1, DNMT3A and DNMT3B SNPs can be a genetic risk factor of ovarian cancer." (PMID 23666104, 2013). "More recently, the expressions of DNMT1, DNMT3A and DNMT3B were examined by immunohistochemistry in ovarian cancers and benign tumors." (PMID 37894317, 2023). "Recently, in primary ovarian carcinoma culture, VEGFA had been shown to promote tumor-initiating cells through Src-DNMT3A-driven miR-128-2 methylation and Bmi1 upregulation." (PMID 35884426, 2022). "We found higher expression of DNMT1 (p = 0.0325), DNMT3A (p = 0.0394), DNMT3B1 (p = 0.0068), DNMT3B3 (p = 0.0171), DNMT3B5 (p = 0.0039), DNMT3B6 (p = 0.0143), and DNMT3B3Δ5 (p = 0.0148) in high-grade ovarian carcinoma." (PMID 36361550, 2022). "In recent studies, it was demonstrated that zebularine and 5-aza-dC down-regulate DNMT-1, DNMT-3a, and DNMT-3b in ovarian cancer cell lines." (PMID 34903991, 2021). "The mRNA levels of DNMT1, DNMT3A, and DNMT3B were strongly elevated in ovarian cancer tissues compared to those in normal ovarian tissues, according to Oncomine." (PMID 31615043, 2019). "Consistent with the data of these reports, we observed that the mRNA levels of DNMT1, DNMT3A, and DNMT3B were elevated in ovarian cancer tissues compared to those in normal epithelial ovarian cells." (PMID 31615043, 2019).
ovarian carcinoma (continued). "Taken together, our results show that 20(S)-Rg3 blocks EMT by targeting DNMT3A/miR-145/FSCN1 pathway in ovarian cancer cells, highlighting the potentiality of 20(S)-Rg3 to be used as a therapeutic agent for ovarian cancer." (PMID 28881818, 2017). "One of the first studies of DNMT expression in ovarian tumors used cancer cell lines and showed an increased expression of DNMT1 and DNMT3B, but not DNMT3A mRNA levels, in ovarian cancer cell lines compared to normal ovarian surface epithelial cells." (PMID 37894317, 2023). "Furthermore, deprivation of DNMT3A restored the expression of miR-199a-3p and resulted in a reduced DDR1 expression in ovarian cancer cells." (PMID 28743276, 2017). "DNMT3A and DNMT3B have been reported upregulated in ovarian cancers." (PMID 28881818, 2017). "Using PCR–RFLP and HRM analyses, we studied the prevalence of the DNMT1 rs8101626, rs2228611 and rs759920, DNMT3A rs2289195, 7590760, rs13401241, rs749131 and rs1550117, and DNMT3B rs1569686, rs2424913 and rs2424932 SNPs in patients with ovarian cancer (n = 159) and controls (n = 180)." (PMID 23666104, 2013). "The results indicated that the mRNA expression of DNMT1, DNMT3b and class I HDACs was increased in ovarian cancers, while the expression of DNMT3a was not different between cancer tissues and normal ovaries." (PMID 23420051, 2013). "The miR-29 family and predicted target genes were among the most strongly anti-correlated miRNA:mRNA pairs; over-expression of miR-29a in vitro repressed several anti-correlated genes (including DNMT3A and DNMT3B) and substantially decreased ovarian cancer cell viability." (PMID 22479643, 2012). "In this study, we collected 142 cases of epithelial ovarian carcinoma samples and 44 cases of benign ovarian tumors for detection of DNMT1, DNMT3a, and DNMT3b protein expressions in order to determine the role of DNMT proteins in ovarian cancer and clinical significance." (PMID 22768205, 2012). "In addition, both 5Aza treatment and DNMT1 and DNMT3A knockdown increased TIMP2 mRNA and protein expression and reduced DNA methylation of the TIMP2 promoter, suggesting that TIMP2 expression is down-regulated by DNA methylation in ovarian cancer cells." (PMID 28620234, 2017). "siRNA silencing of DNMT1 or DNMT3B restored the expression of ALDH1A2 and reduced methylation in ovarian cancer cells, whereas no significant changes in ALDH1A2 expression were observed upon knockdown of DNMT3A." (PMID 31615043, 2019).
myeloproliferative neoplasm (36 papers, 2012 to 2025). A clonal hematopoietic stem cell disorder, characterized by proliferation in the bone marrow of one or more of the myeloid (i.e., granulocytic, erythroid, megakaryocytic, and mast cell) lineages. "DNMT3A mutations have also been identified in patients with MDSs and myeloproliferative neoplasms and are associated with a greater likelihood of progression to AML." (PMID 36119476, 2022). "Early studies demonstrate that Dnmt3a haploinsufficiency transforms Flt3ITD myeloproliferative disease into rapid, spontaneous, complete AML." (PMID 39078434, 2025). "Like DNMT3A, TET2 is considered an early preleukemic mutation associated with the sequential acquisition of additional mutations in AML and myeloproliferative diseases." (PMID 38028538, 2023). "These NGS panels target genes that are associated with multiple hematological conditions, e.g., DNMT3A, TET2, ASXL1, and genes that are implicated in the pathogenesis of specific hematological disorders, e.g., JAK2 for myeloproliferative neoplasms (MPN)." (PMID 36290845, 2022). "The only myeloproliferative neoplasm included in this review presented with a JAK2 and a DNMT3A variant." (PMID 35884491, 2022). "Here, we observed somatic DNMT3A variants in four (11%) out of 37 RUNX1-FPD AMLs, one RUNX1-FPD myeloproliferative neoplasm, and one RUNX1-FPD thrombocytopenia patient." (PMID 35884491, 2022). "In the recent years, DNMT3A (DNA (cytosine-5-)-methyltransferase 3 alpha) and TET2 gene mutations affecting DNA methylation, are detected by genome sequencing in many myeloproliferative neoplasms." (PMID 34945127, 2021). "Despite of the frequently reported Dnmt3a abormality in classical myeloproliferative neoplasms (cMPNs) patients, few research explores how the Dnmt3a is regulated by Jak2V617F mutation." (PMID 34773997, 2021). "Dnmt3a+/− mice on BL6 background developed various myeloid conditions including myeloproliferative disease and myeloid leukemia with 56% penetrance over the course of 2 years." (PMID 33450231, 2021). "We have recently reported that mice harboring a conventional knockout allele of Dnmt3a (Dnmt3a+/- mice) develop either CLL, myeloproliferative disorder or remain healthy by 16 months of age." (PMID 27690235, 2016). "FLT3-ITD, NPM1, and DNMT3A mutations frequently occurred in AML patients and have been found conferred with myeloproliferative neoplasms in mouse model." (PMID 24895580, 2014). "Histological examination of BM, spleen, liver, heart and lungs showed a higher incidence of myeloproliferative neoplasm (MPN)/AML in Dnmt3aR882H/+ mice (37%), reflecting the higher risk of progression to AML of DNMT3A-R882 compared to other DNMT3A mutations." (PMID 40239706, 2025). "Here, we studied the effects of Dnmt3a haploinsufficiency combined with Ptpn11D61Y, a gain-of-function mutation in the protein tyrosine phosphatase SHP2, which is the most commonly mutated gene in juvenile myelomonocytic leukemia (JMML) and is used as a mouse model of myeloproliferative disease." (PMID 29464054, 2018). "In our AML models (MLL-AF9 and DNMT3A/FLT3ITD), as was seen in myeloproliferative neoplasm models, the main source of IL-33 is stromal cells." (PMID 40691440, 2025). "DNA methyltransferase 3a (Dnmt3a) haploinsufficiency, however, transforms Flt3-ITD mutant murine myeloproliferative neoplasms (MPNs) into AML." (PMID 34903841, 2022). "In another study, it was reported that mouse models of CH carrying mutations in Tet2, Dnmt3a, Asxl1, and Jak2 demonstrated that obesity accelerated the size of CH clones and increased the risk of developing a myeloproliferative neoplasm (MPN)-like phenotype, regardless of the specific mutation." (PMID 39119355, 2024).
Obesity (36 papers, 2014 to 2026). Accumulation of substantial excess body fat. "This study demonstrates that the RRTFB improves alleviates obesity and its associated metabolic complications through epigenetic regulation of the DNMT3a/SIRT1/PPARγ axis." (PMID 40909259, 2025). "Together, these data suggest that obesity induced the expansion and transformation of pre-LHSCs/PCs bearing Dnmt3a or Tet2 mutations and contributed to the development of a severe MPN-like phenotype." (PMID 37071471, 2023). "Here, we establish a role for DNMT3A in regulating adipogenesis in vivo and in vitro and demonstrate that DNMT3A deficiency predisposes mice to obesity, even on a normal diet." (PMID 35635747, 2022). "Our data also indicate that even heterozygous loss of Dnmt3a in preadipocytes promotes pro-inflammatory obesity." (PMID 35635747, 2022). "Germline pathogenic variants in DNMT3A were recently described in patients with overgrowth, obesity, behavioral, and learning difficulties (DNMT3AOvergrowth Syndrome/DOS)." (PMID 34315901, 2021). "Accordingly, Dnmt3a ablation in PVH neurons causes obesity and decreased energy expenditure in mice." (PMID 30694175, 2019). "Here, we identify Dnmt3a as a key epigenetic determinant of obesity-associated IR in adipose tissue." (PMID 29091029, 2017). "These include models of Dnmt3a deficiency, heterozygosity of which causes the human overgrowth disorder Tatton-Brown-Rahman Syndrome, which manifest with tibial/femoral length increase, adult onset obesity and brain size alterations." (PMID 41023182, 2025). "Notably, DNMT1 and DNMT3A, highly expressed in individuals with obesity, contribute to the induction of obesity-associated inflammatory responses." (PMID 40620794, 2025). "We extended these studies to determine whether other CHIP mutations such as Dnmt3a also result in similar outcomes in the setting of obesity." (PMID 37071471, 2023). "Thus, we further examined the mechanisms accounting for obesity associated with reduced DNMT3A." (PMID 35635747, 2022). "Our results establish that DNMT3A directly regulates obesity through the adipose tissue, in addition to its role in the hypothalamus, and demonstrate how constitutive loss of DNMT3A creates a domino effect in which excess feeding together with faulty adipocytes lead to obesity." (PMID 35635747, 2022). "Thus, tissue-specific effects of DNMT3A function, which are beneficial in liver but detrimental in adipose tissue, may result in undesired effects if DNMT3A is targeted systemically to treat obesity-associated diseases." (PMID 33235221, 2020). "Transgenic mice with Dnmt3a overexpression display increased inflammation after HFD that is accompanied by increased expression of the tumor necrosis factor-α (TNF-α) and the monocyte protein-1 (MCP-1); increased Dnmt3a expression may also contribute to inflammatory-associated obesity." (PMID 26690877, 2015). "In contrast, heterozygous Dnmt3a KO mice (Dnmt3a+/−) exhibit postnatal phenotypes such as obesity, increased bone length, and behavioral abnormalities, which partially recapitulate human TBRS caused by DNMT3A mutations." (PMID 40630543, 2025). "While this study establishes the DNMT3a/SIRT1 axis as a mechanistic pathway for RRTFB's anti‐obesity effects, several limitations should be acknowledged." (PMID 40909259, 2025). "Collectively, our epidemiological and experimental findings indicate that Dnmt3a-CH promotes the development of obesity and metabolic disease." (PMID 41027007, 2025). "Along the course of our study, a recent report indicated that adipocyte DNMT3a mediates obesity-induced insulin resistance via increasing DNA methylation at the Fgf21 gene." (PMID 40666843, 2025). "To determine the biological consequence(s) of obesity on CHIP-bearing HSC/Ps, we generated obese FBM (leptin-deficient Ob/Ob) mice possessing Tet2–/– or Dnmt3a+/– mutations to mimic the human pre-leukemic condition in the context of obesity." (PMID 37071471, 2023).
Obesity (continued). "Heterozygous germline mutations in DNMT3A lead to Tatton-Brown-Rahman Syndrome (TBRS), characterized by obesity and excessive height." (PMID 35635747, 2022). "Given the marked obesity of Dnmt3a heterozygous mice, we considered the possibility that factors other than hypothalamus-regulated behaviors contribute additively to the increased adiposity." (PMID 35635747, 2022). "We show that heterozygous Dnmt3a-null mice recapitulate the obesity phenotype observed in TBRS along with increased length." (PMID 35635747, 2022). "Taken together, these results confirm a role for DNMT3A in regulation of obesity via early stages of adipogenesis." (PMID 35635747, 2022). "Of notice, in our study, Se supplementation inhibited obesity-induced DNMT3A expression in epididymal adipose tissue." (PMID 35624758, 2022). "While one study showed homozygous ablation of Dnmt3a specifically in hypothalamic Sim1-positive neurons led to hyperphagia and obesity, knockout of Dnmt3a in mature adipocytes protected mice from developing insulin resistance while on a high-fat-diet." (PMID 35635747, 2022). "In obese mouse models, increased DNMT3a expression was observed in adipose tissue, contributing to obesity-related inflammation and insulin resistance." (PMID 34485290, 2021). "In conclusion, SNPs of the DNMT3A and CARM1 genes are associated with BMD, in the latter case probably owing to a strong correlation with obesity and fasting insulin levels." (PMID 33004909, 2020). "Increased expression of DNA methyltransferase 3a Dnmt3a in the adipose tissue of transgenic mice suggests that it contributes to obesity-related inflammation." (PMID 30397228, 2018). "It is thus unclear if direct or indirect (i.e. trans-repression) mechanisms account for the actions of rosiglitazone on Dnmt3a expression in obesity." (PMID 29091029, 2017). "We found that the expression of DNA methyltransferases (DNMT3a and DNMT3b) in adipose tissue-derived macrophages was induced by HFD treatment or obesity-associated factors." (PMID 27530451, 2016). "Next, we verified which DNMTs among the three isoforms in mammals, DNMT1, DNMT3a and DNMT3b, were responsible for the obesity-induced R2 hypermethylation." (PMID 26139044, 2015). "Rosa roxburghii Tratt fermentation broth alleviates obesity via DNMT3a/SIRT1 axis." (PMID 40909259, 2025). "This study substantiates the potential of RRTFB as a phytochemo therapeutic strategy for combating obesity, highlighting its ability to mitigate obesity through DNMT3a/SIRT1‐mediated epigenetic regulation, with flavonoids identified as the primary bioactive components." (PMID 40909259, 2025). "To investigate the relationship between CHIP and obesity, we analyzed several mouse models harboring common CHIP mutations: Tet2, Dnmt3a, Asxl1, or Jak2 on the background of LepOb/Ob (Ob/Ob) mice to mimic the human pre-LHSCs/PCs condition occurring in individuals with obesity." (PMID 37071471, 2023). "Germline heterozygous mutations in DNMT3A lead to Tatton-Brown-Rahman syndrome (TBRS; OMIM: 615879), a dominant disorder characterized by excessive height (~80% of individuals), intellectual disability (~80% of individuals), and obesity (~70% of individuals)." (PMID 35635747, 2022). "Strikingly, this pro-inflammatory program was already activated at 8 weeks in 3A-HET mice, months before development of obesity, suggesting that DNMT3A is required for proper adipocyte differentiation and prevents premature activation of a proinflammatory cascade." (PMID 35635747, 2022). "Given the constitutional loss of DNMT3A that functions across multiple tissues, our TBRS model offers a unique opportunity to study the association between DNA methylation, adipogenesis, and obesity." (PMID 35635747, 2022). "The obesity phenotype was exacerbated by feeding a high-fat diet, which did not cause a similar weight gain in Dnmt3a+/+ littermates." (PMID 34315901, 2021).